LYPD3 (LY6/PLAUR domain containing 3)
Description:
Supports cell migration. May be involved in urothelial cell-matrix interactions. May be involved in tumor progression.
Synonyms: C4.4A
Tractability: Antibody: its Gene Ontology location is reachable by antibodies, with high confidence; UniProt places it where antibodies can reach, with medium confidence; UniProt predicts a signal peptide or a membrane-spanning region.
Gene: Protein-coding gene on chromosome 19 (43,460,787 to 43,465,608, reverse strand). Ensembl gene ENSG00000124466.
Subcellular location: Cell membrane
Subcellular location (Human Protein Atlas): Endoplasmic reticulum; Vesicles
Pathways (Reactome):
Metabolism of proteins: Post-translational modification: synthesis of GPI-anchored proteins
Gene Ontology:
Molecular function: protein binding; laminin binding
Biological process: negative regulation of smooth muscle cell apoptotic process
Cellular component: extracellular region; plasma membrane; membrane
Genetic constraint (gnomAD): Loss-of-function variants: 22 observed, 19.82 expected, observed/expected ratio (o/e) 1.11, 90% interval 0.79 to 1.58. The upper end of that interval is the gene's LOEUF score, 1.58, which puts it in group 6 of 6, group 1 being the genes least tolerant of losing a copy. Missense variants: 471 observed, 476.92 expected, observed/expected ratio (o/e) 0.99, 90% interval 0.92 to 1.07. Synonymous variants: 179 observed, 204.28 expected, observed/expected ratio (o/e) 0.88, 90% interval 0.77 to 0.99.
Homologues: Orthologues: chimpanzee LYPD3 (99% identical), pig LYPD3 (84% identical), guinea pig LYPD3 (81% identical), macaque LYPD3 (81% identical), dog LYPD3 (79% identical), mouse Lypd3 (74% identical), rat Lypd3 (74% identical), rabbit LYPD3 (70% identical). Paralogues in human: LYPD5 (21% identical), PLAUR (20% identical).
Diseases named in the same sentence as LYPD3 in open-access papers:
LYPD3 is named in the same sentence as 52 diseases in open-access papers, as found by Europe PMC text mining. Sharing a sentence is not in itself a finding about the gene and the disease. The quoted sentences say what the papers report.
breast carcinoma (14 papers, 2003 to 2025). "Moreover, activation of the LYPD3 signaling pathway was associated with the endocrine therapy-resistant and metastasis of breast cancer." (PMID 37568077, 2023). "On the other hand, LYPD3 protein expression was exclusively localized in primary and metastatic breast cancer tissues, and it was reported to maintain CRC stemness." (PMID 36816947, 2023). "In contrast to our findings of lower relative protein expression in relation arsenic exposure, enhanced protein expression of LYPD3 has been identified in tissues from urothelial cancers, breast cancers, melanoma, and lung cancers." (PMID 33381488, 2020). "The expression of LYPD3 in breast cancer cell lines varied with MCF-7 cells expressing the highest levels." (PMID 32098331, 2020). "In this study we have demonstrated the importance of LYPD3 in breast cancer cell migration by successfully knocking down the expression of LYPD3 using LYPD3-specific shRNA." (PMID 32098331, 2020). "They showed that inhibiting the activity of this pathway with blocking antibodies against LYPD3 or AGR2 inhibited the growth of endocrine therapy resistant breast cancer in the preclinical model, and again provided the basis for the development of humanized antibodies against AGR2." (PMID 37197416, 2023). "Furthermore, LYPD3 has been demonstrated to be highly expressed in several human malignancies, such as breast cancer, colorectal cancer, esophageal cancer, renal cell carcinomas, and so forth." (PMID 35360840, 2022). "Furthermore, by knocking down LYPD3 expression in the MCF-7 breast cancer cell line we demonstrated that LYPD3 supports both basal and norepinephrine-induced cell migration." (PMID 32098331, 2020). "Interestingly, upregulation of LYPD3 has been observed following cellular stress, however, this is the first study showing that treatment of breast cancer cells with the endogenous stress hormone norepinephrine, can also lead to elevated LYPD3 levels." (PMID 32098331, 2020). "This transcription factor was also shown to induce expression of the membrane receptor LYPD3, and the LYPD3 ligand, AGR2 to promote the growth of endocrine therapy-resistant breast cancers in mice." (PMID 35269877, 2022). "Together, FOXA1 and GRHL2 induce the expression and activity of LYPD3, a Ly6 receptor family member, as well as its ligand AGR2, in mouse models of endocrine resistant breast cancer, as well as patient tumors that progressed on endocrine therapy." (PMID 34680352, 2021). "In this regard, Cocce and colleagues identified the GPI-anchored membrane protein, LYPD3, as a “druggable” downstream target of FOXA1 and the transcription factor, GRHL2 (Grainyhead Like Transcription Factor 2) in endocrine-resistant breast cancer." (PMID 34680352, 2021). "In addition, blocking the downstream pathways activated by LYPD3 and its ligand AGR2 facilitated the progress of endocrine therapy-resistant breast cancer and pancreatic carcinoma 76,77." (PMID 40084259, 2025). "Furthermore, the same research group showed that AGR2 and AGR3 were both co-expressed in estrogen receptor (EsR)-positive breast cancer and can physically interact with LY6/PLAUR Domain Containing 3 (LYPD3 /C4.4a) and extracellular alpha-dystroglycan (DAG-1)." (PMID 35965326, 2022).
lung adenocarcinoma (7 papers, 2016 to 2025). A carcinoma that arises from the lung and is characterized by the presence of malignant glandular epithelial cells. "An increase in LYPD3 levels is connected to the development of lung adenocarcinoma and unfavourable outlook." (PMID 39602465, 2024). "This analysis revealed that the protein levels of both LYPD3 and PPP1R3G were significantly elevated in lung adenocarcinoma tissues compared to matched normal adjacent tissues (p < 0.05 for both; Reference to the supplementary S1A,B)." (PMID 41358202, 2025).
lung carcinoma (7 papers, 2016 to 2025). "Consistently, previous studies also showed that LYPD3 (C4.4A) was overexpressed in lung cancer and played as a tumorigenesis and metastasis-associated cell surface protein." (PMID 34872577, 2021). "This analysis led to the discovery of a 3-gene signature—comprising PPP1R3G, CREG2, and LYPD3—that is characteristic of the resistant lung cancer cells." (PMID 41358202, 2025). "In a pre-clinical trial, an anti-LYPD3 antibody-auristatin conjugate (BAY 1129980) is tested for treatment of LYPD3-expressing non–small cell lung cancer." (PMID 34604071, 2021). "Recently, high protein expression levels of LYPD3 in tumor tissues have been recognized as a biomarker of poor prognosis for lung cancer patients." (PMID 33381488, 2020). "A recent report describes an antibody-drug conjugate targeting LYPD3 which showed efficacy in preclinical mouse models of lung cancer and is currently being tested in clinical trials." (PMID 29371917, 2017). "Five of these markers, CXorf61, DSG3, FAT2, GPR87, and LYPD3, were selected based primarily on their high and broad expression among the lung cancer samples relative to normal lung." (PMID 29371917, 2017). "This suggests that LYPD3 could be a potential therapeutic target in multiple different cancers, and is not solely restricted to breast, oesophageal, pancreatic and lung carcinomas." (PMID 32098331, 2020). "Additionally, the Ly6/PLAUR domain-containing protein 3 (LYPD3) emerged as a novel target for development of a lung cancer targeted therapy, which could be co-developed with a companion imaging agent for the personalized treatment of lung cancer." (PMID 29371917, 2017).
melanoma (6 papers, 2007 to 2025). A malignant, usually aggressive tumor composed of atypical, neoplastic melanocytes. "We stained and visualized the cytoskeleton using phalloidin and found that JUP/AGR2/LYPD3 can help melanoma cells form pseudopodia." (PMID 37924160, 2023). "In the present study, we found that LYPD3 levels were accompanied by a progressive increase in the depth of melanoma infiltration and confirmed the statistical correlation between high LYPD3 level and poor OS and DSS." (PMID 37924160, 2023). "In the present study, we demonstrated that upregulation of JUP/AGR2/LYPD3 signaling promotes melanoma cytoskeleton remodeling and stimulates the formation of new pseudopods." (PMID 37924160, 2023). "We confirmed that the JUP/AGR2/LYPD3 signaling axis promotes F-actin expression, remodels the cytoskeleton and confers a robust invasive phenotype to melanoma cells." (PMID 37924160, 2023). "Our results suggest the presence of Plakoglobin (JUP)/Anterior Gradient 2 (AGR2)/LY6/PLAUR Domain Containing 3 (LYPD3) pro-oncogenic signaling in melanoma." (PMID 37924160, 2023). "Fourth, some studies discussed the association of LYPD3 with the progression of PDAC, melanoma and non-small cell lung cancer." (PMID 36701413, 2023). "Comparison of hub gene expression levels in different cell types was established and showed that LYPD3 was expressed in the highest abundance and upregulated in both melanoma cells and immune cells (green circle and box)." (PMID 37924160, 2023). "It was shown that hyperactivation of the JUP/AGR2/LYPD3 signaling axis contributes to the regulation of melanoma cell stemness and promotes glycolysis through a Glucose Transporter Type 1 (GLUT1)-dependent pathway." (PMID 37924160, 2023). "We demonstrated that JUP regulates Anterior Gradient 2 (AGR2)/LY6/PLAUR Domain Containing 3 (LYPD3) to maintain melanoma stemness and promotes glycolysis." (PMID 37924160, 2023). "Considering that JUP is a homologue of β-catenin and is closely related to β-catenin in many cases to concertedly regulate cell fate, we speculate that there may be a mechanism of JUP/AGR2/LYPD3 signaling regulation in melanoma." (PMID 37924160, 2023). "This study extends the biological significance of the JUP/AGR2/LYPD3 signaling axis to melanoma." (PMID 37924160, 2023). "The JUP/AGR2/LYPD3 signaling axis plays an important role in the malignant features of melanoma." (PMID 37924160, 2023). "The co-expression pattern of LYPD3 and S100A9 was confirmed by multiple immunofluorescence (mIF) staining of the same melanoma resection specimen." (PMID 37924160, 2023). "Our findings suggest that the JUP/AGR2/LYPD3 signaling axis plays an important role in melanoma, but its in-depth mechanism of action is still lacking." (PMID 37924160, 2023).
pancreatic cancer (5 papers, 2007 to 2025). "Of tumor-elevated proteins identified in LMD sampling, 4 additional tumor-associated proteins, COL17A1, VSNL1, LYPD3, and VCAN, were reported in the Pancreatic Cancer Database." (PMID 36266629, 2022). "Of 115 tumor-elevated proteins identified in LMD sampling, 4 additional tumor-associated proteins, COL17A1, VSNL1, LYPD3, and VCAN, were reported in the Pancreatic Cancer Database." (PMID 36266629, 2022).
colorectal cancer (4 papers, 2007 to 2023). A primary or metastatic malignant neoplasm that affects the colon or rectum. "In colorectal cancer models, LYPD3 was found to be preferentially expressed in CSCs and to play a role in maintaining CSCs." (PMID 37924160, 2023).
breast tumour (3 papers, 2003 to 2020). "NE treatment increased the migration of breast tumor cells and upregulated pro-metastasis Ly6/PLAUR domain-containing protein 3 (LYPD3), which was abrogated by β2-AR antagonist ICI-118551, suggesting LYPD3 plays as a potential key mediator in β2-AR driven metastasis." (PMID 33419318, 2020). "Histology confirmed selective LYPD3 expression in primary and metastatic breast tumour samples." (PMID 32098331, 2020).
colon cancer (3 papers, 2007 to 2023). "LYPD3 expression was increased in colon cancer but not rectal cancer tissues." (PMID 36816947, 2023).
carcinoma in situ (2 papers, 2014 to 2023). "Interestingly, LYPD3 expression is markedly attenuated in the non-invasive stage of cutaneous malignant lesions (carcinoma in situ), but re-activated upon transformation to malignant invasive squamous cell carcinoma, especially in the invasive front region." (PMID 37924160, 2023). "LYPD3, encoding for the Ly6/PLAUR domain-containing membrane protein 3, has been shown to be down-regulated upon transition to dysplasia and carcinoma in situ, and being up-regulated again at the invasive front and in local lymph node metastasis of esophageal squamous cell carcinomas." (PMID 24887580, 2014).
endometrial cancer (2 papers, 2021 to 2025). Primary or metastatic malignant neoplasm involving the endometrium (mucous membrane that lines the endometrial cavity). "In previous reports, OGFRP1 unregulated the expressions of LYPD3 and SIRT1 by sponging miR-124-3p in NSCLC and endometrial cancer, respectively." (PMID 33744848, 2021). "TATs highly expressed in cervical cancer include CEACAM5, CD71, CD138, FGFR3, LYPD3, CEACAM6, etc.; VEGF is also highly expressed in ovarian cancer; CD71 and CD138 are highly expressed in endometrial cancer; the TATs highly expressed in uterine sarcoma include B7-H3, DLK1, and EFNA4." (PMID 40046734, 2025).
esophageal cancer (2 papers, 2022 to 2023). A primary or metastatic malignant neoplasm involving the esophagus. "Of the top 20 genes whose expression most correlated with ZNF750 expression in esophageal cancer, 10 were epidermal differentiation and keratinization-related genes, such as LYPD3, KRT6A, KRT16, and IVL." (PMID 37365152, 2023). "It was found that tumor cell expression of LYPD3 correlates with poor prognosis in non-small cell lung cancer (NSCLC), esophageal cancer, and renal cell carcinomas." (PMID 35360840, 2022).
squamous carcinoma (2 papers, 2024 to 2025). "FGFR3, LYPD3, PVRL4, SDC1, and TACSTD2 exhibited significantly elevated expression levels in squamous cell carcinoma relative to adenocarcinoma." (PMID 40046734, 2025).
thymoma (2 papers, 2020 to 2021). A neoplasm arising from the epithelial cells of the thymus. "Furthermore, our in silico analysis has revealed that LYPD3 may be a therapeutic target in multiple cancer types, some of which have not been reported in the literature (testicular germ cell tumours and thymoma)." (PMID 32098331, 2020).
breast adenocarcinoma (1 paper, 2020). "LYPD3 protein staining was localised in the cytoplasm of breast adenocarcinoma cells, with occasional intense staining in cellular membranes." (PMID 32098331, 2020).
diabetic nephropathy (1 paper, 2020). "In an immortalized non-tumorigenic human epidermal cell line (HaCaT), decreased expression of LYPD3 was detected after induction of epithelial–mesenchymal transition by TGFβ, a process already associated with tubulointerstitial fibrosis in diabetic nephropathy." (PMID 32425885, 2020).
epithelial dysplasia (1 paper, 2024). "Furthermore, LYPD3 expression was markedly elevated in epithelial dysplasia and HNSCC tissues compared to normal oral mucosa samples." (PMID 39009906, 2024).
gastric cancer (1 paper, 2021). A primary or metastatic malignant neoplasm involving the stomach. "Thus, we detected the expression levels of LYPD3 and SIRT1 in gastric cancer cells." (PMID 33744848, 2021).
leukemia (1 paper, 2022). A malignant (clonal) hematologic disorder, involving hematopoietic stem cells and characterized by the presence of primitive or atypical myeloid or lymphoid cells in the bone marrow and the blood. "In summary, the relationship between LYPD3, apoptosis, and leukemia remains complex and unclear, and the specific mechanisms and the upstream and downstream molecules that regulate them need to be further studied." (PMID 35360840, 2022).
meningioma (1 paper, 2022). A generally slow growing tumor attached to the dura mater. "In addition, LYPD3 was reported to be normally mostly expressed in meningioma tissues according to the study by Mette C in 2011." (PMID 35360840, 2022).
Miscarriage (1 paper, 2019). A pregnancy that ends at a stage in which the fetus is incapable of surviving on its own, defined as the spontaneous loss of a fetus before the 22th week of pregnancy. "LY6/PLAUR Domain Containing 3 (LYPD3), a gene involved in the post-translational modification of GPI-anchored proteins, was among the most up-regulated transcripts in patients suffering recurrent miscarriage." (PMID 31244343, 2019).
oesophageal cancer (1 paper, 2020). "In oesophageal cancer, LYPD3 is regulated via CREB (cAMP response element binding protein) transcription co-activator signalling, and therefore, it is postulated that norepinephrine regulates LYPD3 through an ADRβ2/cAMP/PKA/CREB/LYPD3 effector pathway." (PMID 32098331, 2020).
pancreatic ductal adenocarcinoma (1 paper, 2023). An infiltrating adenocarcinoma that arises from the epithelial cells of the pancreas. "A study showed that LYPD3 stimulates proliferation, migration, invasion and drug resistance of pancreatic ductal adenocarcinoma (PDAC) cells by interacting with AGR2." (PMID 37924160, 2023).
seminoma (1 paper, 2023). A radiosensitive malignant germ cell tumor found in the testis (especially undescended), and extragonadal sites (anterior mediastinum and pineal gland). "Altogether, these results revealed the key role of TFAP2C in promoting migration and invasion by directly regulating genes such as FOSL1, LYPD3 and ITGA6 in the seminoma cell line, promoting further study to understand its role in seminoma tumorigenesis." (PMID 38123589, 2023).